PDE4D (phosphodiesterase 4D)
Diseases named in the same sentence as PDE4D in open-access papers (continued):
Sharing a sentence is not in itself a finding about the gene and the disease.
atherosclerosis (7 papers, 2010 to 2024). A disease characterized by the build-up of fatty material and calcium deposition in the arterial wall resulting in partial or complete occlusion of the arterial lumen. "The long-term elevation of cAMP levels increases the expression of specific PDE4D isoforms through cAMP-dependent transcription factors in human endothelial cells, and raises histone levels of PDE4D promoter sequences in activated smooth muscle cells, which may cause atherosclerosis." (PMID 38465333, 2024). "It was also suggested that the polymorphisms of the rs2910829 locus may affect the PDE4D gene level and activity changes, alter the intracellular cAMP level and thus promote the formation of atherosclerosis, which is closely associated with the occurrence of cerebral infarction." (PMID 24348782, 2014). "The consistent genetic effect on various atherosclerotic phenotypes suggests that one of the major contributions of the PDE4D gene is to increase atherosclerosis." (PMID 20540798, 2010). "PDE4D selectively degrades the second messenger cAMP in vascular smooth muscle cells and activates macrophages, which is a key signaling molecule mediating proliferation, migration and secretion of cells related to atherosclerosis and plaque stability." (PMID 28225001, 2017). "That can be explained by the role of PDE4D gene in the process of atherosclerosis." (PMID 23799094, 2013). "The upregulation of PDE4D expression selectively degrades cAMP, leading to vascular smooth muscle proliferation and migration and an increased local inflammatory response in damaged vessels, thus inducing the development of atherosclerosis and the occurrence of cerebral infarction." (PMID 24348782, 2014). "Given that atherosclerosis proceeds long before the occurrence of clinical ischemic event, using the severity of carotid atherosclerosis as a phenotype may reduce the complexity and improve the power to detect the PDE4D genetic effect." (PMID 20540798, 2010). "In the present study, we sought to determine whether the PDE4D gene is involved in the pre-clinical atherogenic process, ranging from the early changes in the vessel morphology (i.e. IMT) to a later stage of atherosclerosis (i.e. plaque formation)." (PMID 20540798, 2010).
atopic dermatitis (6 papers, 2019 to 2025). "To investigate the role of PDE4D in atopic dermatitis, we constructed PDE4D knockout (Pde4d−/−) mice, and confirmed a pretty efficiency of Pde4d deletion." (PMID 41059955, 2025). "Genetic knockout validates PDE4D as a key driver and promising therapeutic target for atopic dermatitis." (PMID 41059955, 2025). "The compound displayed good selectivity for PDE4B (IC50 = 6–16 nM) and PDE4D (IC50 = 3–9 nM) isoforms, being a potential therapeutic agent for psoriasis and atopic dermatitis." (PMID 39125619, 2024). "Interestingly, all PDE4 isoforms are expressed in skin lesions of psoriatic arthritis, atopic dermatitis, and discoid lupus erythematosus, with PDE4B and PDE4D being the most prominent in normal dermal fibroblasts." (PMID 39223490, 2024).
childhood asthma (6 papers, 2009 to 2024). "Genome‐wide association analysis demonstrated that PDE4D SNPs, specifically rs1588265 and rs1544791, exhibited protective effects against childhood asthma." (PMID 38730525, 2024). "Elevated levels of seven proteins (TLR4, UBP25, CBR1, Rac GTPase‐activating protein 1 [RGAP1], IL‐21, MICB, and PDE4D) and decreased levels of three proteins (GSTO1, LIRB4 and PIGF) were associated with an increased risk of childhood asthma." (PMID 38730525, 2024). "Our analysis focused on four proteins, IL‐21, MICB, PDE4D, and RGAP1, which exhibited effects in both MR analyses involving risk factors and childhood asthma outcomes." (PMID 38730525, 2024). "Hence, the specific mechanisms by which MICB, PDE4D, and IL‐21 proteins affect the onset of childhood asthma will require further experimental evidence for elucidation." (PMID 38730525, 2024). "Based on the genetic data of 4419 (of 4489) plasma proteins from UK Biobank, our study presents compelling evidence linking 10 plasma proteins (GSTO1, LIRB4, PIGF, IL‐21, MICB, PDE4D, RGAP1, TLR4, UBP25 and CBR1) to childhood asthma." (PMID 38730525, 2024).
colon cancer (6 papers, 2016 to 2025). "Another study implicated PDE4D in the suppression of the AKT-mechanistic target of rapamycin (mTOR)-MYC proto-oncogene, BHLH transcription factor (MYC) signaling pathway, reducing the malignant properties of colon cancer cells." (PMID 40961924, 2025). "Another target gene PDE4D was found functioning in colon cancer and bladder cancer." (PMID 35401884, 2022). "Interestingly, this was not accompanied by altered tumorigenicity and growth dynamics as xenograft in SCID mice arguing against a major oncogenic or tumor-suppressive role of PDE4D in the SW480 colon cancer cell model." (PMID 27602951, 2016). "Western blot assays revealed that forced LINC01138 expression in colon cancer cells SW480 increased the expression of diacylglycerol kinase eta (DGKH) and Phosphodiesterase 4D (PDE4D), whereas resulted in decrease the expression of pyrroline‐5‐carboxylate reductase 1 (PYCR1) and transketolase (TKT)." (PMID 36366731, 2023).
gastric cancer (6 papers, 2019 to 2025). A primary or metastatic malignant neoplasm involving the stomach. "The increased expression of miR-494 inhibits the expression of PDE4D mRNA and protein in gastric cancer cells." (PMID 40129976, 2025). "Homozygous deletion of PDE4D was also identified in breast, lung and gastric cancers which established it as a tumor-promoting gene." (PMID 32617189, 2020). "Additionally, restoration of PDE4D reverse the drug sensitivity of in gastric cancer cells with miR-494 overexpression." (PMID 40129976, 2025).
chronic obstructive pulmonary disease (5 papers, 2011 to 2025). A chronic and progressive lung disorder characterized by the loss of elasticity of the bronchial tree and the air sacs, destruction of the air sacs wall, thickening of the bronchial wall, and mucous accumulation in the bronchial tree. "PDE4D was also associated with mineral bone density, chronic obstructive pulmonary disease (COPD) in Japanese population, and stroke." (PMID 21876611, 2011). "One of the PDE4D inhibitors, roflumilast, is used in clinics to treat chronic obstructive pulmonary disease (COPD)." (PMID 26371509, 2015). "Interestingly, we found that the 5hmC modification level of PDE4D, a drug target for chronic obstructive pulmonary disease (COPD), was significantly increased in the death group and MI group." (PMID 35071229, 2021). "Interfering with PDE4D function significantly inhibited liver metastases, and roflumilast, a PDE4 inhibitor approved for the treatment of chronic obstructive pulmonary disease, was also effective." (PMID 39956959, 2025).
fragile X syndrome (5 papers, 2017 to 2024). A genetic syndrome caused by mutations in the FMR1 gene which is responsible for the expression of the fragile X mental retardation 1 protein. "PDE4D is expressed in layer II/III cortical pyramidal neurons, which play an important role in major mental disorders including fragile X syndrome, autism, and depression." (PMID 31488603, 2019). "BPN14770 is a selective small molecule allosteric inhibitor of PDE4D that was granted Orphan Drug Designation by the Food and Drug Administration (FDA) upon successful completion of a Phase 2 trial in Fragile X syndrome (FXS)." (PMID 37914699, 2023).
Hypertension (5 papers, 2009 to 2023). The presence of chronic increased pressure in the systemic arterial system. "Additionally, in the liver, PDE4D would play a key role in the pathogenesis of hypertension associated with non-alcoholic fatty liver disease." (PMID 38069339, 2023). "Among the cell types associated with hypertension, PDE4D is also expressed in fibroblasts." (PMID 35058564, 2022). "PDE4D deficiency in SMCs and PDE4 inhibitor rolipram reduced Ang II-induced hypertension, and the protective effect of rolipram on hypertension was mainly through PDE4D in SMCs." (PMID 35058564, 2022). "Herein, we reveal that PDE4D (one of PDE4 isoforms) expression is upregulated in the aortas of experimental hypertension induced by angiotensin II (Ang II)." (PMID 35058564, 2022). "This study elucidated PDE4D as a potential target for the treatment of hypertension and, potentially, other cardiovascular diseases." (PMID 35058564, 2022). "To further explore how PDE4D in SMCs influences hypertension, we examined direct vascular function in the knockout mice." (PMID 35058564, 2022). "The authors also show that Pde4d knockout in mouse SMCs attenuates Ang II-induced hypertension and implicate AMPK signalling and MYPT1-MLC phosphorylation in Ang II-induced SMC contraction." (PMID 35058564, 2022). "To further elucidate this association, we investigated a potential mechanism for PDE4D involvement in SMC contraction and hypertension development, and identified the PKA-AMPK-MYPT1-MLC signaling pathway to be a likely candidate." (PMID 35058564, 2022). "In this study, we observed upregulated PDE4D expression in hypertensive mice aortas, which showed that PDE4D contributes to hypertension." (PMID 35058564, 2022). "Indeed, PDE4D expression was increased in the vascular wall of C57BL/6J mice in which hypertension was induced by angiotensin II (Ang II) infusion." (PMID 38069339, 2023). "In conclusion, our study provided that PDE4D in SMCs aggravated Ang II-induced hypertension." (PMID 35058564, 2022). "Furthermore, via EC- and SMC-specific Pde4d knockout hypertensive mice, these models revealed a causal association between SMC Pde4d and vasocontraction in hypertension." (PMID 35058564, 2022). "While PDE4D’s role in the inflammation response is outside the scope of this study, our findings, along with the body of literature evidence, suggest that PDE4D could also contribute to hypertension via inflammation regulation." (PMID 35058564, 2022). "Furthermore, knockout of Pde4d in mouse smooth muscle cells (SMCs) attenuates Ang II-induced hypertension, arterial wall media thickening, vascular fibrosis and vasocontraction." (PMID 35058564, 2022). "In addition, rolipram alleviated hypertension mainly through PDE4D in SMCs." (PMID 35058564, 2022). "Importantly, we demonstrated that rolipram, a pan PDE4 inhibitor, relieved Ang II-induced hypertension mainly by inhibiting PDE4D in SMCs, which suggested that PDE4D might represent a potential therapeutic hypertension target." (PMID 35058564, 2022). "Furthermore, PDE4D, expressed in SMCs instead of ECs, contributed to hypertension development." (PMID 35058564, 2022). "A more recent study showed that overexpression of PDE4D in the liver led to the development of NAFLD and hypertension in mice, which was attenuated by PDE4 inhibitor treatment." (PMID 37887031, 2023). "Consistent with previous reports, our results exhibited that PDE4D upregulated MYPT1 and MLC phosphorylation by inhibiting the PKA-AMPK signaling pathway, inducing SMCs contraction and thereby, hypertension." (PMID 35058564, 2022). "Accordingly, it should not be discounted that PDE4D could further contribute to the development of hypertension by interfering with collagen production in fibroblasts, a possibility warranting future investigation." (PMID 35058564, 2022).
Obesity (5 papers, 2018 to 2025). Accumulation of substantial excess body fat. "The current study assessed the association of PRDM16 gene polymorphism (rs2651899) and PDE4D gene polymorphism (rs295978) with obesity and blood lipids profiles in the Saudi population." (PMID 29890628, 2018). "While the PDE4D (rs295978) polymorphism didn’t show significant effect on risk of obesity or blood lipids profiles." (PMID 29890628, 2018). "In the current study, we have assessed the association between PDRM16/rs2651899 and PDE4D/rs295978 polymorphisms with obesity and blood lipids profiles among the Saudi population." (PMID 29890628, 2018). "This prompted us to look for genetic variants in GNAS, PDE4D, and PRKAR1A, and for methylation alterations of GNAS locus in a cohort of Finnish patients who had developed severe obesity already in early childhood." (PMID 32318528, 2020). "Further, no earlier study has assessed the association of PDE4D polymorphisms with either obesity or lipids profiles." (PMID 29890628, 2018). "In regards to PDE4D/rs295978 polymorphism, the mutated genotypes (GG and CG) were associated with reduced ODD of obesity but was statistically insignificant (OR = 0.5, 95% CI = 0.1969 to 1.5767, p = 0.2 and OR = 0.7, 95% CI = 0.3520 to 1.7490, p = 0.5, respectively)." (PMID 29890628, 2018). "Altogether, PDE4 regulation seems to be implicated in obesity at the level of PDE4B and PDE4D, and an allosteric inhibitor of PDE4D would be effective in the loss of fat mass without changing cognitive function." (PMID 36142518, 2022). "Interestingly, PDE4D level was not changed in patients with obesity, steatosis, or steatohepatitis or in obese (ob/ob) mice but was increased in the human cirrhotic liver and correlated with the levels of COL1A1 mRNA." (PMID 41196648, 2025).
psoriasis (5 papers, 2022 to 2025). An autoimmune condition characterized by red, well-delineated plaques with silvery scales that are usually on the extensor surfaces and scalp. "Indeed, PDE4B and PDE4D were found to be overexpressed in PBMCs from patients with Psoriasis, an inflammatory disease characterized by the dysfunction of dermal fibroblasts." (PMID 37887031, 2023). "Increased ERK activity can lead on the one hand to induce cell proliferation and inhibit cell apoptosis, and on the other hand to increase PDE4D activation, leading to there was no therapeutic synergy between salmeterol and roflumilast in relieving psoriasis." (PMID 35795567, 2022).
bladder cancer (4 papers, 2018 to 2025). "Conversely, low PDE4D expression was associated with poor outcomes in bladder cancer patients." (PMID 40129976, 2025). "We then observed the morphological alterations of cells after the knockdown of PDE4D and found that only the 5637 bladder cancer cells became irregular in shape and extended tentacles." (PMID 30482227, 2018). "The results showed that the overexpression of PDE4D inhibited the proliferation of bladder cancer cells and the knockdown of PDE4D, conversely, promoted the cell growth." (PMID 30482227, 2018). "In TCGA data, a significantly low (cancer vs. normal) PDE4D expression was observed in bladder cancer patients and correlated with their poor prognosis." (PMID 30482227, 2018). "We found that IFN-α also suppressed COX-2 expression by reducing the intracellular cAMP level through TPL2/ERK-mediated PDE4D activity in bladder cancer cells." (PMID 30482227, 2018). "Reduction of the intracellular cAMP level by PDE4D potentiated the antitumor effect of IFN-α against bladder cancer in vitro and in vivo." (PMID 30482227, 2018). "The antitumor effects of IFN-α and MEK inhibition also depend on the PDE4D-mediated cAMP level in bladder cancer cells." (PMID 30482227, 2018). "PDE4D overexpression and knockdown were then performed to further examine the role of PDE4D in the regulation of proliferation and migration in bladder cancer cells." (PMID 30482227, 2018). "Furthermore, the downregulation of intracellular cAMP through PDE4D enhanced the efficacy of IFN-α against bladder cancer in both in vitro and in vivo." (PMID 40129976, 2025). "Considering the important role of PDE4D in the downstream of TPL2-MEK/ERK pathway, PDE4D expression might be a prognostic marker in bladder cancer patients with an aberrant MAPK activation." (PMID 30482227, 2018). "We attempted to determine whether roflumilast induces the PDE4D expression in bladder cancer cells." (PMID 30482227, 2018). "Tissue microarray chips were used to investigate the prognostic roles of PDE4D and tumor progression locus 2 (TPL2) in bladder cancer patients." (PMID 30482227, 2018). "Here we showed that the PDE4D activity was repressed by the constitutive activation of TPL2/ERK in bladder cancer cells and the antitumor effect of IFN-α-induced TPL2/ERK inhibition partially depended on the PDE4D-mediated cAMP level." (PMID 30482227, 2018). "Further analysis of clinical samples indicated that low PDE4D expression and high level of TPL2 phosphorylation were also correlated to the development and poor prognosis in bladder cancer patients." (PMID 30482227, 2018). "Further analysis of clinical samples indicated that low PDE4D expression and high level of TPL2 phosphorylation were correlated to the development and poor prognosis in bladder cancer patients." (PMID 30482227, 2018). "The knockdown of PDE4D also increased the migration of bladder cancer cells and IFN-α (or TPL2 inhibitor) reduced the number of migrated cells only when the PDE4D protein was overexpressed." (PMID 30482227, 2018). "IFN-α down-regulated the cyclooxygenase-2 (COX-2) expression in bladder cancer cells through the inhibition of TPL2/NF-κB pathway; IFN-α also inhibited COX-2 expression by suppressing cAMP signaling through TPL2-ERK mediated PDE4D activity." (PMID 30482227, 2018). "In this study, we found that the induction of PDE4D expression by roflumilast synergized with IFN-α to reduce the cAMP level and potentiated the antiproliferation effect of IFN-α on bladder cancer in both the cell lines and mice xenograft model." (PMID 30482227, 2018). "This study reveals the novel regulatory effects of TPL2 and PDE4D on the antitumor efficacy of IFN-α and MEK inhibitors in bladder cancer treatment." (PMID 30482227, 2018). "Interestingly, study revealed that roflumilast-induced upregulation of PDE4D expression works in concert with IFN-α, and amplifying the antiproliferative action of IFN-α on bladder cancer cells in vitro and vivo." (PMID 40129976, 2025).
bladder cancer (continued). "Additionally, the low PDE4D expression and high pTPL2 levels were found to positively correlate with the age and TNM stages of bladder cancer patients." (PMID 30482227, 2018). "The roflumilast-induced PDE4D did not alter the intracellular cAMP level after 12 h in bladder cancer cells, reinforcing the notion that the PDE4D activity is stringently regulated by compartmentalization in cells." (PMID 30482227, 2018). "Taken together, these data suggested that the induction of PDE4D expression by roflumilast synergized with IFN-α activity to reduce the intracellular cAMP level and potentiates the antiproliferative effect of IFN-α on bladder cancer cells." (PMID 30482227, 2018). "Thus, we aimed to investigate whether the cross-talk between TPL2/MEK/ERK pathway and PDE4D/cAMP signaling mediates the antitumor effect of IFN-α and the potential of these molecules as biomarkers for targeted molecular therapy of bladder cancer." (PMID 30482227, 2018).
cognitive decline (4 papers, 2020 to 2025). "Previously, we reported that PDE4D expression is isoform-specifically altered in post-mortem brains of AD patients and that this expression correlates with the degree of pathology and cognitive decline." (PMID 37306762, 2023). "Most importantly, the in vivo experiment was conducted to provide proof-of-concept of the change in PDE4D isoform signature during AD-related cognitive decline." (PMID 37306762, 2023). "Given the importance of cAMP signaling to long-term and working memory, it is important to understand how age-related changes in PDE4D may contribute to age-related cognitive decline." (PMID 33192469, 2020).